IL21 (interleukin 21)
Diseases named in the same sentence as IL21 in open-access papers (continued):
Sharing a sentence is not in itself a finding about the gene and the disease.
cancer (continued). "The pleiotropic effect of IL-21 is also reflected in a range of clinical trials where IL-21 showed immune stimulatory effects, acceptable toxicity, and antitumour effects in a fraction of cancer patients." (PMID 29849593, 2018). "As IL-21 has been proven capable of inhibiting γδ T 17 cell protumor cell responses, further research on IL-21 should be conducted in human cancer." (PMID 29316940, 2018). "In this study, we have investigated the ability of IL-21 to inhibit FOXP3 induction in purified naïve CD4 T cells in the context of culture supernatants from a number of cancer cell lines." (PMID 28239749, 2017). "Accordingly, the addition of recombinant IL-21 restored the function of intratumoural Tim-3+PD-1+ NK cells both in animal models and in human cancer patients." (PMID 28585539, 2017). "We suggest that not only inducing antigen-specific T cell and innate immune responses but also restoring NK-cell exhaustion via IL-21 signalling are crucial for overcoming cancer immuno-evasion." (PMID 28585539, 2017). "We conclude that Treg induction in naïve T cells is a common phenomenon amongst a number of different cancers and that the ability of IL-21 to counteract this effect is further evidence of its promise in cancer therapy." (PMID 28239749, 2017). "Unsurprisingly, a number of clinical trials of IL-21 administration in cancer therapy have now been initiated, either as a monotherapy or in combination with other agents." (PMID 28239749, 2017). "Molecules targeting TFh cell function, such as PD-1 blocking antibodies and recombinant IL-21 administration are currently being used in therapeutic cancer trials." (PMID 28194154, 2017). "Activation of the cytotoxic programs in NK cells and CD8+ T cells is key for cancer immunotherapy, and consequently early studies provided compelling evidence that IL-21 is a promising immunotherapeutic agent for this disease." (PMID 26966515, 2016). "These facts warrant future development of IL-21 and IL-7 co-expressing whole-cell cancer vaccines and their relevant combinatorial regimens." (PMID 27571893, 2016). "Clinical trials using IL-21 as an adjuvant for cell-based cancer immunotherapy have been encouraging." (PMID 26966515, 2016). "The sustenance of adaptive memory against cancer is also a feature worth noting for IL-21 and IL-7 co-expressing cancer vaccines, since immune memory is responsible for long-lasting protection from cancer recurrences." (PMID 27571893, 2016). "Here we show that co-expression of two cytokine members of the common cytokine receptor γ-chain family, IL-21 and IL-7, in whole-cell cancer vaccines boosts antitumor immunity in a CD4+ and CD8+ T cell-dependent fashion." (PMID 27571893, 2016). "This review will summarize the biological functions of IL-21, and address its role in lymphoid malignancies and preclinical and clinical studies of cancer immunotherapy." (PMID 25961061, 2015). "Clinical phase I-II studies of IL-21 in cancer patients showed immune stimulatory properties, acceptable toxicity profile, and antitumor effects in a fraction of patients." (PMID 25961061, 2015). "It has also been demonstrated in cancer immunotherapy models that there can be a “helper-independent” phenotype of CTLs after immunotherapy that is due to IL-21 at the time of priming." (PMID 25119341, 2014). "Other studies have found that a “helper-independent” phenotype of CTLs in cancer immunotherapy is due to IL-21 at the time of priming and IL-21 has also been demonstrated to upregulate PD-1." (PMID 25119341, 2014). "In view of the relevance to human disease these results have direct therapeutic implications and suggest strategies that boost IL-21 signaling in T cells as novel treatment options for chronic viral infections and cancer." (PMID 23696736, 2013). "IL-2, IL-7, IL-15 and IL-21, sharing a common receptor γ chain (c-γ), control T lymphocyte homeostasis and proliferation and play major roles in regulating cancer-immune system interactions." (PMID 21943235, 2011).
cancer (continued). "One of the latest candidates for solid cancer immunotherapy is Interleukin (IL)-21, a γc-signaling protein of the IL-2 cytokine family with versatile immune-modulating properties." (PMID 22022259, 2011). "Here, we have designed a new comprehensive PK/PD/disease model to predict clinically relevant scenarios of IL-21 treatment following intravenous (IV) subcutaneous (SC) or intraperitoneal (IP) administration in different cancer indications." (PMID 22022259, 2011). "For example, immunomodulatory cytokines including IL-2, IL-12, or IL-21 would be effective adjuvants in the enhancement of impaired ADCC in patients with cancer." (PMID 20029417, 2010). "Suchfindings are vital to adoptive immunotherapy and its implications in cancer.The potential for immune-related therapy in the treatment of cancer meritsfurther investigation into the interplay between IL-2 and IL-21." (PMID 19277104, 2008). "Several studies have reported the potent cytotoxic effect of IL-21 against cancer cells." (PMID 40176196, 2025). "Clinical trials of interleukin-21 use for adoptive cell therapy in cancer immunotherapy." (PMID 38638431, 2024). "IL-2, IL-12, IL-15, IL-18, and IL-21 could promote NK cells entry into S and G2/M phases of the cell cycle in cancer patients or healthy subjects, and thus have been used to induce ex vivo NK cell proliferation." (PMID 39286242, 2024). "Furthermore, IL-21 showed antitumor effects in the treatment of patients with advanced cancer, with minimal side effects in several clinical trials." (PMID 38638431, 2024). "Therefore, IL-21 has been proposed as a good candidate for cancer treatment, either alone or in combination with other therapeutic agents." (PMID 38638431, 2024). "Interleukins, such as IL-2, IL-12, IL-15, IL-18, and IL-21, glucocorticoids, such as cortisone acetate and hydrocortisone, and ascorbic acid can promote the ex vivo proliferation of NK cells in healthy people or cancer patients." (PMID 39286242, 2024). "IL-21 is known to be cytokines stimulating the activation of NK cell however, the level of IL-6 in NK-cancer microenvironment may decide the fate of NK cells on hypoxic-induced HCC." (PMID 37501379, 2023). "IL-21, like many other ILs, undergoes an alteration during cancer, not only in the brain." (PMID 37759505, 2023). "On the other hand, IL-18 and IL-21 contribute to the effector function of NK cells against cancers." (PMID 37501379, 2023). "IL-21 also reverses NK depletion to promote cancer regression in mice." (PMID 35606854, 2022). "Moreover, we found that CD226, which has cytolytic activity against cancer cells, was enriched on NK-EVs by IL-15 + IL-21 stimulation." (PMID 34316033, 2022). "Interleukin 21 (IL21) is an immune agonist that is an attractive cancer immunotherapeutic." (PMID 34869384, 2021). "Therefore, a complete human anti-PD-1 antibody fused with IL-21 will be more effective in cancer therapy." (PMID 33574265, 2021). "The requirement for frequent dosing might be an obstacle to the success of IL21-based therapies in cancer patients." (PMID 34869384, 2021). "In contrast, the expression of genes regulating immune cell trafficking (e.g., CXCL13, CXCL9, XCL2, CCL5), T-cell activation and clonal expansion (e.g., CD27, CD28, ICOS, IL21, IL2) were massively decreased in 9p21-loss tumors across multiple cancer types/subtypes." (PMID 34556668, 2021). "In the future, treatment that combines immune checkpoint inhibition therapy and cytokine therapy with IL-21 may be developed for chronic viral infection and cancer." (PMID 34502427, 2021). "Taken together, our study unravels a previously unappreciated CD4+ T cell-derived IL-21–BATF axis that could provide therapeutic insights to enhance effector CD8+ T cell function to fight cancer." (PMID 33809259, 2021). "Interleukin-21 is a type I cytokine and a member of the common cytokine receptor gamma-chain (cg-chain) family that has emerged as a promising immune therapeutic for the treatment of cancer." (PMID 32457754, 2020).
cancer (continued). "In combination with the observation that IL-21 has been used in a variety of clinical trials for the treatment of malignant tumours, it is necessary to further evaluate the pharmacological and physiological effects of IL-21 in the field of non-Hodgkin's lymphoma (NHL) therapy." (PMID 32704112, 2020). "Toll-like receptor 4 (TLR4)-induced monocyte inflammation is important for induction of IL21+ TFH-like cells, which operate in IL21-IFNγ-dependent pathways to induce plasma cell differentiation and thereby create ideal conditions for M2b macrophage and cancer progression." (PMID 33365025, 2020). "However, it is likely that the use of IL21 in cancer immunotherapy will be investigated in this direction." (PMID 32582698, 2020). "The use of cytokines from the IL-2 family (also known as the common gamma chain cytokine family) such as IL-2, IL-7, IL-15 and IL-21 to activate the immune system of cancer patients is currently the one of the most important fields of cancer immunotherapy research." (PMID 31703694, 2019). "More recently, exogenous IL-21 was shown to inhibit the expression of FoxP3, the cardinal transcription factor associated with regulatory T cells, in human CD4+ T cells following encounter with cancer cells – in a manner similar to TGF-β blockade." (PMID 29854291, 2018). "IL-21 and Rapamycin can be used concurrently to raise and maintain antigen specific Tscm cells in vitro for purposes of augmenting immunotherapy strategies against cancers." (PMID 28904691, 2017). "IL-21 likewise strongly supports the activation of adaptive anti-cancer immunity." (PMID 27832300, 2017). "Besides its direct apoptotic effect, IL-21 alone or combined with anti-CD20 monoclonal antibody (mAb) (rituximab) can also indirectly kill the IL-21-insensitive cancer cells by activating NK cell-dependent cytotoxic effects." (PMID 26966515, 2016). "IL-27 similar to other cytokines studied as potential anti-cancer agents, e.g. IL-18 or IL-21, may have a dual role in immune-regulation." (PMID 26657115, 2015). "On the other hand, the activation of immune-regulatory pathways by IL-21 may limit the efficacy of IL-21-based cancer immunotherapy and support the concept that IL-21 may act as a double-edged sword in cancer." (PMID 25961061, 2015). "IL-2, IL-7, IL-15 and IL-21 are of particular interest in cancer immunotherapy." (PMID 21943235, 2011). "Thus, immunomodulatory cytokines including IL-2, IL-12, or IL-21 would be effective adjuvants in the enhancement of impaired ADCC in patients with cancer." (PMID 20029417, 2010). "Targeting NK cells by combining DNA vaccine and immune modulators such as adjuvants (TLR agonists) and/or cytokines (e.g. IL-2, IL-15 or IL-21) could also be an exciting option as recently proposed in cancer immunotherapy." (PMID 20090916, 2010). "Finally, since injection of anti–CTLA-4 antibodies can also promote IL-21 production, our findings may be relevant to autoimmune adverse events in cancer patients receiving checkpoint immunotherapy, where autoantibodies frequently emerge." (PMID 37466652, 2023). "Therefore, cancer cells might repress the expression of IL-21 via their EVs to create a favorable microenvironment for the cancer cells to proliferate." (PMID 28798470, 2017). "Recent advances in the pathogenesis of CD and the discovery that the inflamed gut of CD patients contains high levels of Th17-type cytokines (e.g., IL-17A, IL-21, IL-22), which are mitogenic for epithelial cancer cells, could explain this apparent contradiction." (PMID 23109839, 2012). "The bifunctional protein, αCD20-IL-21 fusokine, obtained by fusion IL-21 to anti-CD20 antibody Rituximab, demonstrated superior anti-cancer potential compared to its individual components." (PMID 38638431, 2024). "IL-21 was fused to the monoclonal antibody IMAB362 (Zolbetuximab) that binds to Claudin18.2, a target antigen specific to cancer cells." (PMID 38638431, 2024).
cancer (continued). "Another category of cells which has therapeutic potential for ACT is NK cells and previous reports have shown IL-21 can be used to expand and improve therapeutic efficacy of CD19 CAR γδT cells or CAR NKT for cancer immunotherapy." (PMID 38638431, 2024). "IL-21 promotes cytotoxicity of CD8+ T cells and NK cells and has been evaluated as a cancer therapy in phase I and II clinical trials." (PMID 37339051, 2023). "Interleukin-21 (IL-21) is a crucial cytokine involved in regulating the function of CD8+ T cells and has emerged as a potential target for cancer immunotherapy." (PMID 38090585, 2023). "With the emergence of cytokine therapy for cancer, the four cytokines of the common cytokine receptor γ chain (γc, CD132) family, containing interleukin-2 (IL-2), IL-7, IL-15, and IL-21 are dictated to regulate the T cell stemness formation and maintenance." (PMID 38049832, 2023). "IL21 was proposed as an alternative to cytokines belonging to the same family such as IL2 and IL15, for cancer therapy." (PMID 35323193, 2022). "Utilizing these characteristics, IL-21 performed much better than IL-2 or IL-15 during in vitro generation of antigen-specific CD8+ CTL and in an in vivo murine model of cancer immunotherapy." (PMID 35432319, 2022). "Here we describe four formats of novel IL21-based antibody–cytokine fusion proteins, targeting the extra domain A (EDA) of fibronectin and explore their potential for cancer treatment." (PMID 35323193, 2022). "We, therefore, sought to assess the CD8+ T cell-intrinsic requirement of BATF downstream of IL-21 signaling, its role in effector CD8+ T cell differentiation and function in cancer, and its utility as a potential immunotherapeutic target." (PMID 33809259, 2021). "In particular, studies have found a critical role for interleukin (IL)-21, a cytokine produced primarily by CD4+ T cells, in facilitating a CD8+ T cell response in both cancer and chronic infection." (PMID 33809259, 2021). "Recent preclinical studies showed that recombinant IL21 synergizes with CTLA-4 and PD-1 blockade to inhibit cancer." (PMID 34869384, 2021). "GrB secretion is induced by IL-3, IL-10, and IL-21 and block CD4+ and CD8+ T cell proliferation; on note, IL-21 has shown relevance in modulating cancer immunity." (PMID 32054102, 2020). "Interleukin 21, another member of the IL2 family, is one of the last cytokines investigated for the clinical use in cancer treatment." (PMID 32582698, 2020). "Thus, IL-21 potentially selects for the long-term maintenance of a restricted, but highly efficient pool of antigen-specific T cells in the host – with a strong influence on disease control (cancer, chronic infections) and survival, a key observation with regard to the cellular therapy of cancer." (PMID 29854291, 2018). "Altogether, this suggests that in a cancer setting, TH9 cells are capable of maintaining IL-9- and IL-21-secreting potential, at least long enough to carry out their anti-cancer functions in vivo." (PMID 27832300, 2017). "For example, immunomodulatory cytokines, including interleukin (IL)-2, IL-12, or IL-21, would be effective adjuvants in the enhancement of impaired ADCC in patients with cancer." (PMID 20029417, 2010). "Addition of IL-21 along with IL-15 in the culture media improved the transfection efficiency of human epidermal growth factor receptor-2 (HER-2) chimeric antigen receptor (CAR) T cells and enhanced the cytotoxic activity against HER-2-positive cancer cells." (PMID 38638431, 2024). "The role of IL-21/IL-21R in cancer development remains obscure and has not been extensively investigated in faithful in vivo models." (PMID 38720319, 2024). "When synergized with other factors, IL-21 exerts a pivotal role in TSCM cell attainment and expansion, exemplified by the synergy with lactate dehydrogenase (LDH) inhibitor in a mouse model of pmel-1 specific TCR-T cell adoptive cancer immunotherapy." (PMID 38049832, 2023).
cancer (continued). "Considering these assumptions, it is not surprising that IL-21 has become an important target for the creation of novel treatment strategies to modulate immunity and inflammation in cancer." (PMID 37759505, 2023). "In all cancer tissues, regardless of degree of differentiation, the value of Il-21/IL-22 mRNA ratio was higher comparing to a control group (respectively: G1 vs. C p = 0.003405; G2 vs. C p = 0.008114; G1 vs. C p = 0.007473)." (PMID 34300224, 2021). "As will be described later, IL-21 has been clinically tested for malignant tumors using the activation of CD8+ T cells by IL-21, but this has not been successful due to side reactions such as liver damage." (PMID 34502427, 2021). "In nonlymphoid organs where off-target tissue damage can have devastating effects (e.g., brain), IL-21 may help guide CD8 T cells toward a mixed TRM-TEX differentiation state and improve immunotherapy outcomes for chronic infections and cancer." (PMID 32971931, 2020). "In humans, IL-21 has been tested as a non-targeted free cytokine in several cancer indications, but despite the promising preclinical data and early phase I clinical data, development of this approach has not progressed further than phase II testing." (PMID 32457754, 2020). "In the autologous cell transplant setting, where cells from cancer patients usually do not expand well, the use of IL-21 can “rescue” the expansion so that enough cells can be manufactured for treatment." (PMID 33282892, 2020). "Our data also suggest that IL-21 could be beneficial as a therapeutic agent across a variety of cancers, due to its ability to inhibit FOXP3 induction across all the cancer cell lines tested." (PMID 28239749, 2017). "It is noteworthy that beyond IL-9 and IL-21, TH9 cell-derived IL-3 could additionally contribute to the induction of adaptive anti-cancer immune responses." (PMID 27832300, 2017). "Similarly to TGFβ blockade, IL-21 was able to potently inhibit baseline FOXP3 induction in naïve T cells and FOXP3 induction as a result of the addition of cancer cell supernatants." (PMID 28239749, 2017). "In addition, IL-21 activates cytotoxic programs in both CD8+ T and NK cells, thus providing potent cytotoxic effector arms against cancer cells." (PMID 28585539, 2017). "Furthermore, the utilization of IL15 in combination therapy with other cytokines (e.g. IL-21 or GMCSF), or co-stimulatory molecules (CD40) is a potential avenue to be explored to improve current cancer immunotherapy." (PMID 26822794, 2016). "However, the role of IL-21/IL-21R in cancer development remains controversial and has not been extensively investigated in faithful in vivo models." (PMID 38720319, 2024). "Using neoantigen peptides with a VV armed with IL-21 did not improve survival of the mice, but it resulted in better outcomes compared with the use of neoantigens plus Poly I:C, an adjuvant commonly used in cancer vaccines." (PMID 37586771, 2023). "However, IL-21 is able to potentiate ADCC mediated by NK cells in vitro and in vivo, and this effect may be relevant for antibody-based cancer immunotherapy." (PMID 25961061, 2015). "Importantly, NK cell dysfunction in some cancer patients may impair their ADCC activity, which can be restored by in vitro stimulation with IL-21." (PMID 25961061, 2015). "An insensitive range of IL-21 doses with similar efficacy is not unreasonable, considering that the drug respectively inhibits or induces NKs and CTLs, two cells which complement one another in the process of cancer targeting." (PMID 22022259, 2011). "However, there are no published results about combination therapies using both IL21 and ICB in human cancer patients." (PMID 34869384, 2021).